IL33 (interleukin 33)
Diseases named in the same sentence as IL33 in open-access papers (continued):
Sharing a sentence is not in itself a finding about the gene and the disease.
histoplasmosis (1 paper, 2021). A disease caused by the fungus Histoplasma capsulatum. "Significant differences in the median values of IL-1β, TNF-α, IFN-γ, IL-18, IL-17A, IL-33, IL-13, and CXCL8 were reached in all the groups studied, suggesting that these cytokines play a role in the inflammatory processes associated with histoplasmosis and pneumocystosis." (PMID 34829225, 2021). "Significant differences in median values of SP-A, IL-1β, TNF-α, IFN-γ, IL-18, IL-17A, IL-33, IL-13, and CXCL8 were found among all the groups studied, suggesting that these cytokines play a role in the local inflammatory processes of histoplasmosis and pneumocystosis." (PMID 34829225, 2021).
HIV-1 infection (1 paper, 2018). The type species of lentivirus and the etiologic agent of acquired immunodeficiency syndrome (AIDS). "Collectively, this data extends our understanding of the regulation of T cell function by the IL-33/ST2 axis during HIV-1 infection." (PMID 30564243, 2018).
immune thrombocytopenia (1 paper, 2019). "One study claimed that IL-33 expression decreased in patients with immune thrombocytopenia." (PMID 31877138, 2019). "Elevated ST2 levels plus normal or low IL-33 expression might interfere with coagulation in cases of DENV infection, as they do in cases of immune thrombocytopenia." (PMID 31877138, 2019).
intestinal infectious disease (1 paper, 2021). An infectious disease involving a pathogenic inflammatory response in the intestinal mucosa. "Exploring the crucial and diverse roles of the IL-33/ST2 axis during infections may help in the development of therapeutic interventions for a range of intestinal infectious diseases." (PMID 33654214, 2021).
intestinal parasite infection (1 paper, 2024). "nILC2 locates at barrier tissues which are crucial for tissue homeostasis and primarily IL-33-responsive, while iILC2 is not resided in peripheral tissues in the steady state but can be elicited at many sites by intestinal parasite infection or IL-25/IL-33 treatment." (PMID 39559705, 2024). "The extent of functional redundancy between IL-33 and IL-25 for intestinal parasitic infections is still unclear, but experiment evidence indicated that IL-33 and IL-25 may largely exert a co-operative action." (PMID 39559705, 2024).
invasive breast carcinoma (1 paper, 2016). A carcinoma that infiltrates the breast parenchyma. "In 40 female patients with invasive breast carcinoma we analyzed IL-33, IL-33R and VEGF expression in tumor cells in order to investigate the relevance of experimental findings in mice for corresponding human pathology." (PMID 26919112, 2016).
joint disease (1 paper, 2012). "Expression of ST2 on mast cells was shown to be critical for disease pathology in the CIA model, thus suggesting a critical role for IL-33-mediated activation of mast cells in joint disease." (PMID 23087690, 2012). "IL-33 has been extensively shown to potently induce Th2-driven inflammation, and thus it came as a great surprise that the absence of IL-33-mediated signaling results in attenuated joint disease." (PMID 23087690, 2012).
keratoconjunctivitis (1 paper, 2017). Inflammation of both the cornea and the conjunctiva. "The phenotype of AKC-like lesions in IL33tg mice suggests that mast cells in keratoconjunctivitis are activated in response to IL-33, which is overexpressed in the ocular surface epithelium in vivo." (PMID 28855579, 2017). "In a transgenic mouse line hK14mIL33tg, with the expression of interleukin-33 (IL-33) driven by a keratin 14 promoter, keratoconjunctivitis developed spontaneously between 18 and 22 weeks of age under specific-pathogen-free conditions." (PMID 28855579, 2017). "The ocular surface inflammation in IL33tg mice does not subside with age, possibly because of sustained IL-33 expression in the epithelium, and therefore the keratoconjunctivitis occurred in IL33tg might be a chronic disease model for AKC." (PMID 28855579, 2017).
kidney infection (1 paper, 2016). "Research concerning the role of IL-33 in kidney infection is relatively limited, and a few reports are focused on cisplatin or Candida albicans-induced renal injury." (PMID 26943125, 2016).
knee osteoarthritis (1 paper, 2024). "Overall, the results indicate that IL-33 has a therapeutic function in the treatment of knee osteoarthritis and may be a novel target for treatment of the underlying causes of KOA." (PMID 39172956, 2024).
leiomyoma (1 paper, 2018). A well-circumscribed benign smooth muscle neoplasm characterized by the presence of spindle cells with cigar-shaped nuclei, interlacing fascicles, and a whorled pattern. "However, serum levels of IL-33 were significantly higher in leiomyoma patients as compared to the controls." (PMID 30205617, 2018). "IL-33 was detected in sera of ~50% leiomyoma patients and ~20% of control patients." (PMID 30205617, 2018).
lentivirus infection (1 paper, 2019). Virus diseases caused by the Lentivirus genus. "To identify the potential pro-survival function of IL-33 on MSCs, we tested the cell viability, apoptosis, and proliferation of MSCs after lentivirus infection." (PMID 31547872, 2019).
liver dysfunction (1 paper, 2023). "Despite this, as was the case for iNKT cells, activation of MAIT cells during LT was closely associated with both early release of IL-33 and severity of liver dysfunction after graft reperfusion." (PMID 37228593, 2023). "Like iNKT cells, and in clear contrast to γδ-T cells, activation of MAIT cells during LT was closely associated with both release of IL-33 immediately after graft reperfusion and severity of liver dysfunction occurring during the first three post-operative days." (PMID 37228593, 2023).
lumbar disc herniation (1 paper, 2018). "Here, we showed that a spinally delivered inhibitor of IL-33 expression, the lentiviral vector LV-shIL-33, significantly attenuated the mechanical allodynia in rat models of noncompressive lumbar disc herniation." (PMID 29329586, 2018). "Thus, the aim of the present study was to test whether the inhibition of spinal IL-33 expression could significantly influence the development and progression of radicular pain, using a rat model of noncompressive lumbar disc herniation." (PMID 29329586, 2018). "Thus, the purpose of this study is to investigate the expression of IL-33 and its receptor ST2 in the dorsal spinal cord and to elucidate whether the inhibition of spinal IL-33 expression significantly attenuates pain-related behaviors in rat models of noncompressive lumbar disc herniation." (PMID 29329586, 2018). "Moreover, to determine which cell types express IL-33 and ST2 in a rat model of noncompressive lumbar disk herniation, double staining was performed using anti-IL-33 or anti-ST2 antibodies and antibodies specific for neurons (NeuN), astrocytes (GFAP), microglia (OX-42), or oligodendrocytes (Olig-2)." (PMID 29329586, 2018).
lymphoid tumor (1 paper, 2019). "Additionally, and since ST2 immunoreactivity coincides with a decrease of E-cadherin in metastatic lymphoid tumor cell membrane, we evaluated the effect of IL-33 on the transcript levels of classical EMT markers (E-cadherin, N-cadherin and vimentin)." (PMID 31281317, 2019).
lymphopenia (1 paper, 2022). Reduction in the number of lymphocytes. "Interestingly, IL-33 signaling was not necessary for lymphopenia-induced proliferation (LIP) in the spleen of syn recipients, as we observed a similar number of ST2fl/fl and ST2WT donor CD4+ T cells." (PMID 35503257, 2022). "IL-33 stimulation of CD4+ T cells was not required for lymphopenia-induced expansion, however." (PMID 35503257, 2022).
meningitis (1 paper, 2024). A disorder characterized by acute inflammation of the meninges of the brain and/or spinal cord. "Consequently, IL-33 and its receptor ST2 may surface as crucial targets for SS2 prevention and therapeutic co-administration in meningitis treatments." (PMID 38980021, 2024).
mesothelioma (1 paper, 2024). A usually malignant and aggressive neoplasm of the mesothelium which is often associated with exposure to asbestos. "Importantly, our data shows that 2 central cytokines modulating eosinophil fate (i.e., IL-5 and IL-33) do not significantly modify tumour growth kinetics in a mouse model of mesothelioma." (PMID 39471751, 2024).
microcytic anemia (1 paper, 2022). Anemia in which the red blood cell volume is decreased. "Additionally, strong positive relation has been detected in comparison of galectin-1 and IL-33 (r = 0.870; p = 0.001), galectin-1 and IL-1 (r = 0.795; p = 0.001) and IL-33 and IL-1 (r = 0.826; p = 0.001) values in serum of CRC patients with diagnosed microcytic anemia." (PMID 35611243, 2022).
microscopic polyangiitis (1 paper, 2015). Microscopic polyangiitis (MPA) is an inflammatory, necrotizing, systemic vasculitis that affects predominantly small vessels (i.e. small arteries, arterioles, capillaries, venules) in multiple organs. "IL-33 levels were higher in patients with granulomatosis with polyangiitis than in patients with microscopic polyangiitis (P = 0.012)." (PMID 25802482, 2015).
mitral valve disease (1 paper, 2021). "The present study is the first one to assess the involvement of the IL-33/ST2 pathway in the development of mitral valve disease." (PMID 33669101, 2021). "In summary, this study has identified IL-33 as a new pathway involved in the development of myxomatous mitral valve disease." (PMID 33669101, 2021). "However, the possible role of the IL-33/ST2 in mitral valve disease has not been elucidated." (PMID 33669101, 2021).
mRss (1 paper, 2023). "Serum level of IL-33 shows a weak positive correlation with mRss, conversely serum level of sST2 does not show correlation with mRss." (PMID 35877052, 2023).
Myalgia (1 paper, 2020). "Comorbidities, degree of myalgia, muscle weakness, fatigue and tolerance of physical activity were neither associated with significantly higher concentrations of sST2 or IL-33." (PMID 32222805, 2020).
myeloid neoplasm (1 paper, 2018). Proliferation of myeloid cells originating from a primitive stem cell. "Given the importance of IL-1 and IL-33 in the development of myeloid neoplasms and the expression of IL1RAP on LSCs, targeting this receptor by mAbs is a promising strategy." (PMID 29868474, 2018).
myelosuppression (1 paper, 2019). Myelosuppression or bone marrow suppression is a condition in which bone marrow activity is decreased, resulting in fewer red blood cells, white blood cells, and platelets. "Our presented data reveal a previously unknown function of IL-33 in promoting HSC regeneration after radiation-caused myelosuppression." (PMID 30999922, 2019).
myositis (1 paper, 2024). "According to our results, the elevated cytokines found in the myositis seronegative patients (IL-6, IL-23, IL-12p70, IL-33, and CXCL8) are related to a Th17 profile." (PMID 39456842, 2024). "Therefore, we suggest a possible differential immune response in seronegative myositis mediated by an induction of the Th17 inflammatory response, through IL-6, with maintenance of the Th17 pathway by IL-23 and IL-33." (PMID 39456842, 2024). "We found higher serum levels of IL-10, IL-6, CXCL8, IL-1β, IL-33, IFN-γ, TNF-α, IL-23, and IL-17A in myositis patients compared to the HSs." (PMID 39456842, 2024).
neuroendocrine tumors (1 paper, 2025). "Our results suggest that pre-treatment measurement of IL-33 may serve as a useful biomarker for predicting poor early therapeutic outcomes in patients with neuroendocrine tumors." (PMID 40943444, 2025). "Importantly, we calculated a clinically relevant cut-off value for IL-33 of 146.5 pg/mL as a potential prognostic marker for therapeutic response in patients with neuroendocrine tumors." (PMID 40943444, 2025).
nosocomial infection (1 paper, 2017). An infection acquired in a hospital or other healthcare setting. "The increases in IL33 and sST2 were significantly greater in patients that developed nosocomial infection and organ dysfunction than similarly injured patients that did not (P < 0.05)." (PMID 28742815, 2017). "Dynamic changes in IL33 and soluble suppression of tumorigenicity 2 (sST2) levels were measured in the plasma and correlated with levels of the type 2 cytokines and nosocomial infection." (PMID 28742815, 2017). "IL33 levels were already markedly elevated on the first blood draw after injury and correlated with increases in IL4, IL5, and IL13 as well as nosocomial infections." (PMID 28742815, 2017).
ocular infections (1 paper, 2025). "Further studies are needed to assess the immunomodulatory role of IL-33/ST2 signaling in ocular infections." (PMID 40512033, 2025). "Our findings reveal divergent innate immune responses between bacterial and fungal endophthalmitis and emphasize the immunomodulatory function of IL-33 in ocular infections." (PMID 40512033, 2025). "While exploring these differences falls outside the current scope, future studies should include a broader spectrum of pathogens to better elucidate IL-33’s role across various types of ocular infections." (PMID 40512033, 2025).
oral lichen planus (1 paper, 2019). Oral lichen planus is a chronic inflammatory oral condition of unknown aetiology characterized by T-cell-mediated chronic immune response and abnormal epithelial keratinization cycle. "Consequently, in conclusion, oral lichen planus is a mucocutaneous disease mediated by a Th1 predominant response, where IL-33 may be important and related to the maintenance of the OLP inflammatory process." (PMID 31792433, 2019).
osteitis (1 paper, 2023). "We observed that higher values of IL-33 are associated with higher values of the CT osteitis score, the relation being statistically significant (B = 0.086, t = 5.505, p < 0.001, 95% CI [0.054, 0.117])." (PMID 38137606, 2023). "Moreover, references regarding the evaluation of inflammation, both at the immunological and imaging level, as well as the association of IL-33 with the severity of osteitis, are extremely sparse." (PMID 38137606, 2023). "In our study population, elevated expressions of IL-33 levels within the inflamed nasal mucosa were directly correlated with computed tomography osteitis scores, and their mean values were statistically significant." (PMID 38137606, 2023). "Postoperatively, in subjects with poor outcomes, imagistic osteitis severity was evaluated, and IL-33 expression was measured." (PMID 38137606, 2023).
ovarian dysfunction (1 paper, 2024). The inability of the ovaries to function. "Given that IL-33 is closely associated with inflammation-associated diseases, its dynamic variation during the progression of ovarian insufficiency might mirror ovarian reserve and function for POI patients." (PMID 39713054, 2024). "Given that POI is a continuum of compromised ovarian function, we wonder whether IL-33 is associated with the development of ovarian insufficiency." (PMID 39713054, 2024).
papilloma (1 paper, 2021). A benign epithelial neoplasm that projects above the surrounding epithelial surface and consists of villous or arborescent outgrowths of fibrovascular stroma. "The papillomas in Mcpip1eKO mice were characterized by increased protein levels of IL-6, IL-33 and TGF-β1." (PMID 34903245, 2021).
parasite (1 paper, 2017). "Finally, the role of HpARI in parasite infections was addressed using Nippostrongylus brasiliensis infection, a parasite which (unlike H. polygyrus) migrates through the lung and leads to early IL-33-dependent type 2 responses." (PMID 29045903, 2017).
peripheral arterial disease (1 paper, 2025). A disorder of the arteries supplying the upper and lower extremity and the visceral organs. "In peripheral arterial disease, IL-33 co-localizes with NLRP3 inflammasome components in calcified vessels, implicating IL-33-associated inflammation in calcification initiation." (PMID 40959491, 2025).
peritoneal cancer (1 paper, 2023). A peritoneum cancer that is located in the inside of the abdomen. "In preclinical models, IL-33 delays metastatic progression of peritoneal cancer via induction of an allergic tumor microenvironment in which eosinophils, CD4+ T cells, and macrophages contribute to anti-tumoral effects." (PMID 37064719, 2023).
pertussis (1 paper, 2023). A contagious bacterial respiratory infection caused by Bordetella pertussis. "LASSO modeling also revealed positive association between pertussis IgG levels with CB concentrations of T-cell-derived cytokines IL-2, IL-17A, and IL-31, but in contrast to tetanus, APRIL was negatively associated with pertussis, as was IL-33." (PMID 37251388, 2023). "At this time point, BAFF and IL-33 were associated with higher 12-month pertussis IgG levels, and APRIL and IL-22 were associated with tetanus." (PMID 37251388, 2023). "Only BAFF and IL-33 showed positive association at the early (6-month) post-vaccine time point, while none of the biomarkers measured at 12 months were associated with sustained pertussis IgG levels." (PMID 37251388, 2023). "Using a least absolute shrinkage and selection operator (lasso) regression model, cord blood (CB) plasma IL-2, IL-17A, IL-31, and soluble CD14 (sCD14) were positively associated with pertussis IgG levels at 12 months, while CB plasma concentrations of APRIL and IL-33 were negatively associated." (PMID 37251388, 2023). "In CB samples, plasma IL-2, IL-17A, IL-31, sCD14, and switched memory B cells were positively associated, whereas APRIL, IL-33, non-switched memory B cells, and plasmablasts were negatively associated with 12-month pertussis IgG levels." (PMID 37251388, 2023).
pneumococcal meningitis (1 paper, 2012). An acute purulent infection of the meninges and subarachnoid space caused by Streptococcus pneumoniae, most prevalent in children and adults over the age of 60. "IL-1β, IL-2, IL-4, IL-10, IL-12p70, IL-17, RANTES, TNF-α, IL-18 and IL-33 were not significantly altered in the plasma of mice with pneumococcal meningitis compared to sham controls." (PMID 22455545, 2012). "IL-2, IL-4, IL-10, IL-12p70, IL-17, IFN-γ, TNF-α, IL-18 and IL-33 were not altered in brain homogenates of mice with pneumococcal meningitis compared to sham controls." (PMID 22455545, 2012).
pterygium (1 paper, 2025). A wedge-shaped fibrovascular lesion arising from the bulbar conjunctiva and extending to the cornea. "Gene expression profiling of pterygium highlighted an IL-33 and IL-4 gene expression signature, along with an increased presence of M2 macrophages, emphasizing their role in promoting fibrosis—a hallmark feature of pterygium." (PMID 40243577, 2025). "Several lines of evidence, including the highest expression of CHIT1, high prevalence of M2 macrophages, and elevated expression of IL33, suggest that this yeast could actively contribute to the development of pterygium rather than being a coincidental finding." (PMID 40243577, 2025).
relapsing remitting MS (1 paper, 2018). "Our previous studies showed that IL-33 contributed to the shape of the transcriptome in patients presenting with the clinically isolated syndrome event but prior to diagnosis of clinically definite relapsing remitting MS." (PMID 30562364, 2018).
renal carcinoma (1 paper, 2020). A carcinoma arising from the epithelium of the renal parenchyma or the renal pelvis. "A recent study also investigated serum IL33 levels and tumor IL33 expression via immunocytochemistry for renal cancer patients." (PMID 32707675, 2020). "However, yet another study described an adverse prognostic impact from the low renal cancer expression of IL33 at the mRNA level." (PMID 32707675, 2020). "Studies on several malignancies (including renal cancer) suggest that the IL33/IL33Rα axis could be important in tumorigenesis through exerting direct effects on malignant cells or indirectly through effects on stromal cells, including altering the regulation of tumor angiogenesis." (PMID 32707675, 2020).